EGFR (epidermal growth factor receptor)
Diseases named in the same sentence as EGFR in open-access papers (continued):
Sharing a sentence is not in itself a finding about the gene and the disease.
lung cancer (continued). "Amivantamab plus chemotherapy has been proved to be an efficient treatment strategy for non–small-cell lung cancer (NSCLC) with epidermal growth factor receptor (EGFR) exon 20 insertions." (PMID 38585010, 2024). "Clinical trials in progress are assessing potential combination activity of the AURKA inhibitor alisertib with the EGFR inhibitor osimertinib (e.g., NCT04085315) in metastatic EGFR-mutant lung cancer." (PMID 38639476, 2024). "Preliminary cell counting kit-8 results showed that most of the compounds exhibit excellent antitumor activity against epidermal growth factor receptor wild-type lung cancer cells NCI-H1299, A549 and NCI-H1437." (PMID 38398589, 2024). "A study made by Seto in 2021 enrolled a total of 124 lung cancer patients with confirmed wild-type EGFR, with an age between 75 and 94 years, who voluntarily chose between chemotherapy and palliative care." (PMID 39195131, 2024). "The enrichment of ER and AR pathways in M4 was consistent with the transcriptomics analysis of EGFR‐driven group (Group 1) in this study, further supporting the involvement of hormonal pathways in lung cancer development." (PMID 39036344, 2024). "EGFR exon 19 deletion has been reported in only two lung cancer patients with GI metastases, both of which were squamous cell carcinomas." (PMID 38957515, 2024). "In TKI-resistant lung cancer cells, the administration of gefitinib induces autophagy-mediated degradation of EGFR as a protective mechanism against its targeting, resulting in resistance that is dependent on the T790M mutation." (PMID 38794196, 2024). "We confirmed both in vitro and in vivo that YAP1/WWTR1/TEAD-dependent transcription is acutely activated following osimertinib treatment in EGFR mutant lung cancer and pharmacologic and genetic ablation of this complex strongly suppresses persister cells." (PMID 38658677, 2024). "Previous reports have suggested that EGFR is involved in HCV infection and that FUT8 can promote EGFR dimerization and phosphorylation in lung cancer cells." (PMID 38253527, 2024). "A high level of AXL activation plays an important role in EGFR-driven NSCLC cells treated with the EGFR-TKI Osimertinib and the development of the intrinsic resistance of EGFR-mutated lung cancer." (PMID 38607003, 2024). "In colon cancer, it can guide adjuvant therapy, while in lung cancer, it can assist in anti-EGFR therapy." (PMID 38774326, 2024). "Ongoing study of PD‐1/PD‐L1 inhibitors in combination with EGFR‐TKIs in EGFR‐TKIs‐resistant non‐small cell lung cancer." (PMID 39631794, 2024). "Afatinib is an orally effective epidermal growth factor receptor (EGFR) tyrosine kinase inhibitor (TKI) used in the treatment of ERBB1-mutant lung cancer, and lapatinib has been widely applied in treating ErbB2-overexpressing breast cancer." (PMID 38173048, 2024). "Epidermal growth factor receptor (EGFR) is a cell surface receptor commonly found in certain types of cancer, such as brain or lung cancers, often in mutant hyper-active forms." (PMID 38727261, 2024). "In this study, significant differences in age and sex were also observed between patients with ALK‐positive and EGFR‐positive lung cancers, although the effects of age and sex on tumor markers are unclear." (PMID 38400801, 2024). "Secondly, it should be noted that our study specifically focused on EGFR-mutant lung cancer cells (del 19 or L858R/T790M) and their EMT-mediated resistance to EGFR-TKIs." (PMID 39766891, 2024). "To identify the compounds with potent inhibitory effects on EGFR wild-type lung cancer cells, we modified gefitinib through a click reaction by introducing a 1,2,3-triazole moiety to its structure." (PMID 38398589, 2024). "In the present study, more ALK‐positive lung cancers were CYFRA21‐1‐positive with higher CYFRA21‐1:CEA ratios compared with EGFR‐positive lung cancers." (PMID 38400801, 2024). "We also found that a high expression of EGFR is correlated with the poor survival of patients with lung cancer." (PMID 39453005, 2024).
lung cancer (continued). "Omicron variant SARS-CoV pseudoviral particles exhibited heightened infectivity in human angiotensin-converting enzyme 2 (hACE2)-expressing HEK293 and A549 lung cancer cells accompanied by increased EGFR pathway activation in infected cells." (PMID 39291996, 2024). "We then cocultured the macrophages in 384-well plates with GFP+ PC9 cells, a human EGFR mutant lung cancer cell line." (PMID 38483480, 2024). "Prior work from our group and others revealed that NF-κB signaling is activated upon EGFR oncogene inhibition in human lung cancer as a stress and survival response." (PMID 38049664, 2024). "In this study, we constructed an in vitro EMT model of EGFR-mutant lung cancer organoids to identify potential EMT-regulating compounds." (PMID 39766891, 2024). "Targeted therapies such as EGFR inhibitors have been developed to target this pathway in lung cancer patients." (PMID 38905286, 2024). "Because the overexpression of EGFR is noted in 50% of patients with lung cancer and the inhibition of the mitotic regulator polo-like kinase 1 (PLK1) can enhance radiation sensitivity, EGFR-positive NSCLC cells were targeted by the siPLK1-NP." (PMID 39339205, 2024). "NSCLC, which accounts for the majority of lung cancer cases, has shown promising results with vaccines and targeted drugs like epidermal growth factor receptor (EGFR) inhibitors Erlotinib and Gefitinib." (PMID 39062777, 2024). "This has been shown therapeutic effects in EGFR-activating mutant lung cancer cells that display intrinsic or acquired resistance to EGFR-TKI." (PMID 39595619, 2024). "Approximately 85% of patients with lung cancer present with NSCLC, with up to two-thirds harbouring actionable driver mutations, most commonly occurring in the epidermal growth factor receptor (EGFR)." (PMID 38668049, 2024). "Genome-wide CRISPR screens, to either knock out or overexpress all protein-coding genes in cancer cell lines, revealed the landscape of pathways that cause resistance to the EGFR inhibitors osimertinib or gefitinib in EGFR mutant lung cancer." (PMID 38658677, 2024). "Disrupting the interaction between RAS and PI3-kinase diminishes the growth and survival of EGFR-mutant lung cancer cells." (PMID 38921583, 2024). "In this study, we sought to elucidate the relationship between demographic and clinical factors and epidermal growth factor receptor tyrosine kinase (EGFR-TK) positivity in patients with advanced-stage lung cancer at a tertiary care center in Pakistan." (PMID 39429333, 2024). "Furthermore, the usefulness of adjuvant therapy using osimertinib for earlier pathological stage IA lung cancer with EGFR mutation is being verified in the ADAURA2 trial The positioning of UFT in relation to osimertinib may become an issue with regard to the target stage of the ADAURA2 trial, too." (PMID 39255996, 2024). "These compounds have the potential to be used as a therapeutic approach for treating EGFR-mutant lung cancer." (PMID 39404419, 2024). "Currently, antibodies against specific lung cancer targets like anti-EGFR, anti-VEGF, and anti-CD147 are under study." (PMID 38389925, 2024). "Drawing from reports indicating that the up-regulation of AXL kinase and its ligand GAS6 can confer resistance to EGFR-targeted therapy in lung cancer, we investigated the expression levels of these genes in both lung and melanoma persister cells." (PMID 38473364, 2024). "In patients with lung cancer that had spread to the brain, we saw EGFR alterations were most identified in intracranial-only progression (67%) as compared to both CNS and extracranial-progression (40%) and extracranial-only progression (37%), P = .08." (PMID 38680992, 2024).
lung cancer (continued). "We next analyzed the public scRNA-seq data of consecutive biopsies at the treatment naïve (TN), residual disease (RD) and progressive disease (PD) stage from an EGFR-mutant lung cancer patient with squamous transition along with TKI therapy failure." (PMID 39687207, 2024). "We anticipate that our current research into novel and specific EGFR-TKIs using the ChemDiv database will be helpful in identifying new compounds with therapeutic potential against lung cancer." (PMID 38625872, 2024). "This study aims to train and independently validate an EGFR mutation state prediction system using PET/CT Inception V3 CNN to screen lung cancer patients for EGFR TKI treatment eligibility." (PMID 39735601, 2024). "We conclude that EGFR is a crucial target for developing targeted therapeutics for cancers including lung cancer." (PMID 39453005, 2024). "There was little evidence of a viability effect when used as a single agent in EGFR mutant lung cancer at concentrations shown to disrupt TEAD binding." (PMID 38658677, 2024). "Compounds that promote the degradation of mutant EGFR have proven effective in suppressing the growth of lung cancer cells." (PMID 38921583, 2024). "Using EGFR-mutant lung cancer as a representative system, we extended prior investigations in two dimensions to address this unsolved fundamental challenge." (PMID 39604408, 2024). "We show that YAP1/WWTR1/TEAD-dependent transcription is acutely activated following treatment of EGFR mutant lung cancer cells with EGFR inhibitors and that prevention of YAP1/WWTR1 activation strongly suppresses cancer cell persistence." (PMID 38658677, 2024). "Currently, there are several ongoing early-stage clinical trials (NCT01869166, NCT03182816, NCT04153799) examining the use of EGFR-targeted CAR T cell therapies in the treatment of lung cancer." (PMID 38622705, 2024). "Current drug therapies for lung cancer can be divided into chemotherapeutic agents and new antibody-based cancer medications, also known as EGFR tyrosine kinase inhibitors." (PMID 39311354, 2024). "EGFR inhibition led to an increase in the populations of CD8+ T cells, dendritic cells and M1-like tumour-associated macrophages in mouse lung cancer models." (PMID 39395265, 2024). "In this study, we used comprehensive scRNA-seq and ST analysis to identify changes in the expression of apoptosis-related genes after EGFR-TKI treatment and to assess tumor heterogeneity in EGFR-mutated lung cancer." (PMID 39122703, 2024). "Such sensitivity enabled mapping key lung cancer signalingsites, such as EGFR autophosphorylation sites Y1197/Y1172 and drugtargets." (PMID 39038167, 2024). "There is a large unmet need to optimize immunotherapy strategies in EGFR-mutant lung cancer to improve patient outcomes." (PMID 39318388, 2024). "For this reason, EGFR acts as a tumor marker and becomes an attractive tool in molecular lung cancer target therapy." (PMID 38234663, 2024). "It has also been shown that 5 μM UA and an anti-EGFR antibody, cetuximab, more effectively inhibited the invasive potential of A549 lung cancer cells than any of the compounds alone." (PMID 39457512, 2024). "These factors underpin EGFR’s role as an ideal target for lung cancer therapy and intervention, thereby offering fresh perspectives in the development of novel anti-cancer drugs targeting EGFR." (PMID 38389925, 2024). "In this study, we successfully developed and demonstrated a theranostic liposomal system simultaneously capable of treating and imaging EGFR-expressing lung cancer." (PMID 38339090, 2024). "ICIs were administered to only 22% of patients with EGFR-mutated lung cancer, and they had shorter TTNT of EGFR-TKI compared to other patients." (PMID 38347279, 2024). "In conclusion, this study has provided valuable insights into the anti-angiogenic effects of HAT in HUVECs and its influence on EGFR TKI resistance in lung cancer cells." (PMID 38338342, 2024).
lung cancer (continued). "The decreased transcription of GCLC and GSS through the inhibition of NRF2 emerged as a mechanism of mutant EGFR/T790M resistance to EGFR inhibition in lung cancer." (PMID 39001381, 2024). "The oncogenic receptor tyrosine kinases are key to lung cancer malignant transformation, as evidenced by the clinical successes of EGFR, MET, and EML4-ALK inhibition by small molecule therapeutics." (PMID 38827327, 2024). "Our study showed that DUSP22 acts as an EGFR phosphatase in lung cancer cells, inhibiting EGFR activity and its crosstalk with c-Met." (PMID 38877005, 2024). "Epidermal growth factor receptor (EGFR)-activating mutations are found in patients with non-small cell lung cancer (NSCLC), which is the major subtype of lung cancer." (PMID 38904022, 2024). "For example, exosomes from EGFR-19del Lewis lung cancer cells transfer active EGFR-19del to dendritic cells, inducing an unresponsive state that inhibits anti-tumor immunity." (PMID 39737074, 2024). "A [U-13C5]glutamine tracing analysis of acquired EGFR-TKI-resistant lung cancer cell lines has unveiled a critical dependency on glutamine for supporting TCA cycle activity and glutathione (GSH) biosynthesis." (PMID 38921453, 2024). "We investigated the impact of tumor marker values on performance status (PS) and distant metastasis in patients with ALK‐positive and EGFR‐positive lung cancer." (PMID 38400801, 2024). "The PI3K-Akt, MAPK, and NF-kappa B signaling pathways and AP-1 are involved in the upregulation of PD-L1 induced by different EGFR-TKI resistance mechanisms that promote immune escape in lung cancer." (PMID 38758372, 2024). "Hypomethylation of EGF and EGFR leads to increased expression levels of these genes, presumably leading to higher activity of this vital pathway and driving lung cancer development." (PMID 39036344, 2024). "Lung cancer cells largely exposed to conventional chemotherapy, mainly EGFR-tyrosine kinase inhibitors (TKI) (e.g., gefitinib, erlotinib, and afatinib), acquire stem-like properties that contribute to chemoresistance and tumor relapse in vitro and in vivo." (PMID 38398217, 2024). "The model used was able to locate different mutant forms of epidermal growth factor receptor (EGFR) in blood collected from lung cancer patients." (PMID 39001524, 2024). "Using gefitinib as a positive control, we employed the cell counting kit-8 (CCK-8) method to assess the in vitro antitumor activity against EGFR wild-type lung cancer cells NCI-H1299, A549 and NCI-H1437." (PMID 38398589, 2024). "It behaves as a growth factor for lung cancer via the activation of epidermal growth factor receptor (EGFR)." (PMID 39351437, 2024). "(Epidermal Growth Factor Receptor) is a protein that is often overexpressed in solid tumors, including lung cancer and brain metastasis." (PMID 38886844, 2024). "Further research is warranted to explore and elucidate the underlying mechanisms responsible for the difference in CYFRA21‐1 values between ALK‐ and EGFR‐positive lung cancers." (PMID 38400801, 2024). "suggest that the conjoint utilization of gefitinib and betulinol can transcend the resistance observed in EGFR wild-type/kras-mutated NSCLC cells to gefitinib, heralding a new pathway for the treatment of such lung cancer manifestations." (PMID 38515565, 2024). "EGFR tyrosine kinase inhibitors (TKI) are the standard-of-care therapy for advanced EGFR-mutant non–small cell lung cancer (NSCLC)." (PMID 38276867, 2024). "Our results support a combined EGFR and ERK1/2 targeting strategy for overcoming resistance in EGFR TKI-resistant lung cancer, as demonstrated in one recent study." (PMID 38877005, 2024). "Our results indicate that for EGFR mutant lung cancer, disabling signals from EGFR makes the cells more vulnerable to macrophage-mediated destruction." (PMID 38483480, 2024). "PPL sensitized lung cancer cells to EGFR-TKI and induced potent cytotoxic effects at low concentrations." (PMID 39449797, 2024).
lung cancer (continued). "EGFR-TKIs as first- and second-line treatment have improved the prognosis and quality of life of advanced lung cancer patients, but inevitably lead to drug resistance." (PMID 39184039, 2024). "Subsequently, we selected six different lung cancer cell lines and performed genetic sequencing of the EGFR exons 19–21." (PMID 38918360, 2024). "In lung cancer, for example, de novo activating alterations in EGFR, KRAS, ROS1, ALK, RET, and NTRK rarely coexist." (PMID 38938274, 2024). "We aimed to enhance the inhibitory activity against wild-type lung cancer cells by modifying the structure of EGFR-TKIs." (PMID 38398589, 2024). "On the other hand, PRMT5, as a key oncogenic regulator, promotes the EMT process in human lung cancer cells through the EGFR/AKT signaling axis, thereby exacerbating resistance development." (PMID 38525426, 2024). "Erlotinib exhibited potent cytotoxicity in EGFR TKI-sensitive PC9 human lung cancer cells, which was diminished when PC9 cells were co-cultured with HUVECs." (PMID 38338342, 2024). "EGFR in lung cancer cells became more difficult to degrade and its thermal solubility curve shifted significantly to the right After adding DHA." (PMID 38778121, 2024). "The process raises the possibility of increased persistence in cells upon drug rechallenge, consequently escalating the frequency of DTP formation and potentially enhancing rates of drug resistance like EGFR-resistant lung cancer cases." (PMID 39138145, 2024). "We found that critical driver alterations, including canonical EGFR and KRAS mutations, were detected across the spectrum of lung cancer precursors." (PMID 38798564, 2024). "This scFv has been demonstrated to efficiently deliver siRNA or SPOINs into EGFR positive lung cancer cells both in vitro and in vivo." (PMID 38589859, 2024). "Accordingly, targeting these mutated EGFRs with EGFR‐TKIs represents a major advance in the targeted therapy of NSCLC and the first successful targeted therapy against lung cancer." (PMID 39044361, 2024). "We observed similar effects using GFP+ MGH119-1 cells, a patient-derived EGFR mutant lung cancer cell line." (PMID 38483480, 2024). "Together, our data suggest that DRD1 can reduce the phosphorylation and total expression of EGFR protein in lung cancer cells." (PMID 38572507, 2024). "There are monoclonal antibodies that are against the extracellular domain of EGFR, for example, one is stoxymab, which is made to treat patients with lung cancer." (PMID 38234663, 2024). "EGFR, the first oncogene discovered, is a transmembrane protein and has become an eye-catching therapeutic target in lung cancer." (PMID 38831321, 2024). "The co-occurrence of EGFR and KRAS mutations negatively affects lung cancer development by inducing oncogenic stress and leading to synthetic lethality." (PMID 38938274, 2024). "The complex of SHC1 and EGFR was the potential therapeutic target to restrain lung cancer metastasis." (PMID 38602568, 2024). "In EGFR-mutant lung cancer cell lines displaying EMT features, a downregulation of miR200c was observed, attributable to the increased level of ZEB-1 in these cells." (PMID 39766891, 2024). "Development of effective strategies to manage the inevitable acquired resistance to osimertinib, a third-generation EGFR inhibitor for the treatment of EGFR-mutant (EGFRm) non–small cell lung cancer (NSCLC), is urgently needed." (PMID 38451729, 2024). "It inhibits lung cancer cell proliferation, expedites apoptosis, and diminishes angiogenesis, invasion, and metastasis by blocking EGFR signaling." (PMID 38389925, 2024). "CRISPR screens proved that mutations of Polybromo-1 (PBRM1) gene attenuate the effects of EGFR inhibitors in lung cancer by enhancing the continuity of AKT signaling." (PMID 39696697, 2024).